SMAD1 (SMAD family member 1)
Diseases named in the same sentence as SMAD1 in open-access papers (continued):
Sharing a sentence is not in itself a finding about the gene and the disease.
cancer (84 papers, 2009 to 2025). A tumor composed of atypical neoplastic, often pleomorphic cells that invade other tissues. "An emerging feature of muscle wasting in cancer is the progressive loss of NMJs integrity due to reduced Smad1/5/8 signaling." (PMID 38052214, 2023). "Given the evidence associating high SMAD1 expression with oncogenesis in other types of cancers, we investigated its effect in MM patients." (PMID 34134766, 2021). "There are many reports of Smad1 in cancers and its association with advanced cancer stage and metastasis." (PMID 27027434, 2016). "The association of Smad1 with advanced cancer stage and migration are well documented." (PMID 29299158, 2017). "Therefore, SMAD1 is implicated in stage 1 to stage 3 of cancers." (PMID 34138687, 2021). "The intricate interplay between MEK/ERK/SMAD1 signaling and the glyoxalase system in prostate cancer underscores the complexity of the molecular networks governing cancer phenotypes." (PMID 38785990, 2024). "The crosstalk between MEK/ERK and SMAD1 in governing EMT underscores the intricate regulatory networks that contribute to the metastatic potential of cancer cells." (PMID 38785990, 2024). "Recent studies have shed light on the profound impact of MEK/ERK/SMAD1 signaling in the context of specific cancers, offering insights into the molecular mechanisms that drive tumorigenesis." (PMID 38785990, 2024). "In parallel, the transcription factor activity related to pro-metastatic response (SMAD1,2,3 and HNF1a) and cancer cell maintenance (OCT4, and ATF1) was similarly increased at 4 h and remained pronounced through the 8 h time point following CM incubation." (PMID 38398186, 2024). "The coordinated actions of MEK/ERK and SMAD1 shed light on the interconnected pathways that facilitate the dissemination of cancer cells throughout the body." (PMID 38785990, 2024). "The convergence of MEK/ERK/SMAD1 signaling with other crucial systems, such as the glyoxalase system, further highlights the interconnected nature of cellular processes in cancer." (PMID 38785990, 2024). "Research efforts are focused on deciphering the molecular intricacies that dictate the divergent outcomes of MEK/ERK/SMAD1 signaling in various cancer contexts." (PMID 38785990, 2024). "For instance, previous research has shown that BMP2 stimulation induces the phosphorylation of SMAD1/5 in cancer cells." (PMID 38520036, 2024). "Understanding the multi-layered roles of MEK/ERK/SMAD1 signaling in cancers is pivotal for unraveling the complexities of this disease and developing targeted therapeutic strategies." (PMID 38785990, 2024). "Next, we focused on Smad1, which is thought to promote the invasive and metastatic potential of certain types of cancer, and examined the expression level of Smad1 in JEG-3 and HTR-8/SVneo cells under UCHL5 inhibition." (PMID 37762005, 2023). "A study by Feng Qu reports that the growth, invasion, and migration of cancer cells can be inhibited through the ALK2/SMAD1 pathway." (PMID 34138687, 2021). "As anticipated, silencing of LRG1 was able to dramatically impair CAFs-induced EMT accompanied by decreased phosphorylation of Smad1/5 in cancer cells." (PMID 34930899, 2021). "BMPs belong to the TGFβ superfamily, and BMP4-dependent SMAD1/5/9 signaling is known to have a role in vascular calcifications and various cancers." (PMID 34944071, 2021). "Several studies highlight an important role for SMAD1 in promoting cell invasion and metastasis in different types of cancers." (PMID 34134766, 2021). "SMAD5 is the major component of the SMAD1/5/9 complex that is often activated by BMP in several cancer types." (PMID 33426064, 2020). "On the other hand, its direct target, Smad1 over-expression, interferes with the miR-199a-3p anti-proliferative effect on cancer evolution." (PMID 32102477, 2020).
cancer (continued). "The mechanism responsible for the downregulation of BMPR2 in EBNA1-expressing and EBV-infected carcinoma cells in vitro is unclear, but the fact that these cells showed robust Smad1/5/8 phosphorylation suggests that ACVR2A or ACVR2B can substitute for BMPR2." (PMID 32708289, 2020). "Our finding that EMT depends on TGF-β-induced ID1 expression has implications for the role of SMAD1/5 and the IDs in cancer." (PMID 29376829, 2018). "Halofuginone decreased immunostaining of phospho-Smad2/3 and phospho-Smad1/5/8 in cancer cells in vivo." (PMID 29156807, 2017). "There were also associations unique to each cancer type, including USF1 and SMAD1 for BRCA, FOXF2 for HNSC, and NFE2L2 and NR3C1 for UCEC." (PMID 28139702, 2017). "In the present study, we found that GDF15 facilitated cancer stemness and radioresistance via activation of Smad1/5, as demonstrated in both cellular and animal studies." (PMID 27903972, 2017). "As shown, specific knockdown SMAD1 substantially increased ROS levels and suppressed cancer stemness." (PMID 27903972, 2017). "Previous studies have also shown that BMP4 can induce EMT in human cancer cells and that SMAD1 participates in the BMP4-induced EMT process." (PMID 27027434, 2016). "Aliquots of total protein extracts from MVEC cells exposed for 2.5 hours to CM of cancer cells were analyzed by Western blot probed for p-SMAD1/5 and p-SMAD2." (PMID 23226264, 2012). "Several studies have reported different, in some cases, opposing transcriptional responses to activation of the canonical TGF-β/Smad2 pathway versus the alternative TGF-β/Smad1/Smad2 signal in normal and cancer cells." (PMID 20442782, 2010). "Among cancers with significant SMAD1 alterations, GBMs had the highest fold change." (PMID 39629919, 2025). "However, the context-dependent effects of MEK/ERK/SMAD1 signaling in cancers add a layer of complexity to therapeutic interventions." (PMID 38785990, 2024). "The dysregulation of the glyoxalase system, including Glo II, is implicated in cancer aggressiveness, drug resistance, and intricate crosstalk with signaling pathways such as MEK/ERK/SMAD1, highlighting its relevance in cancer diagnostics and treatment strategies." (PMID 39351318, 2024). "The crosstalk and convergence of the MEK/ERK and SMAD1 signaling pathways present an intriguing avenue for developing combination therapies that effectively disrupt multiple nodes in the intricate signaling network fueling cancer progression." (PMID 38785990, 2024). "SMAD1 inhibits the growth, invasion, and migration of cancer cells." (PMID 34138687, 2021). "To examine if there is a potential correlation between SMAD1 expression and activation of the apoptotic pathway in MM, we analyzed the Cancer Cell Line Encyclopedia (CCLE), a large database of gene expression profiling for more than 1000 human cancer cell lines." (PMID 34134766, 2021). "Our previous studies demonstrated that high shear force could result in the cell cycle arrest and cell death in multiple types of cancer cells through Smad1/5 signaling." (PMID 32630668, 2020). "Here, we show that forkhead box F2 (FOXF2) functions as a master transcription factor for reprogramming cancer cells into an osteomimetic phenotype by pleiotropic transactivation of the BMP4/SMAD1 signaling pathway and bone-related genes that are expressed at early stages of bone differentiation." (PMID 31222004, 2019). "In line with these notions that SMAD1 functioned as oncogene involving in promotion of cancer cell growth and invasion, we have unambiguously demonstrated that expression of SMAD1 was significantly suppressed in response to baohuoside-I treatment, which exclusively depended on miR-144 up-regulation." (PMID 29260980, 2018). "SMAD family member 1 (Smad1) have been involved in metastatic progression of many cancer types." (PMID 29299158, 2017).
cancer (continued). "Additionally, the cancer stemness phenotype promoted by GDF15 was significantly inhibited in SMAD1 knockdown cells, as shown in two HNC cell lines." (PMID 27903972, 2017). "Furthermore, the MEK/ERK/SMAD1 signaling pathway, known for its involvement in cellular processes such as proliferation, differentiation, and apoptosis, has gained attention in the context of cancer progression." (PMID 38785990, 2024). "Moreover, further mechanism studies have elucidated that Smad1/5, matrix metalloproteases, transforming growth factor-β and chemokine signaling might be regulated by shear forces to affect the cancer cell fates." (PMID 32630668, 2020). "For example, lung tumors with very low or undetectable phospho-Smad1/5/8 levels may very well happen to suffer from BMP receptor mutations, however, the fact that at least a subset of these cancers expresses high LKB1 levels supports the model provided by our exhaustive biochemical analysis." (PMID 26701726, 2016). "Injury-induced populations were highest for TFs related to cell proliferation, self-renewal, and cancer involving both intrinsic (E2F family, MYC, and ZFX) and extrinsic (HIF1a, EPAS1/HIF2a, NFYB, LEF1, GLI2, VDR, and SMAD1/3/5) pathways." (PMID 38905342, 2024). "To further evaluate the regulation of PCTK1 in cancer cell phenotype and chemoresponse through BMPR1B-SMAD1/5/8 in CRC, we treated PCTK1-KD HT-29 cells with two SMAD1/5/8 inhibitors, LDN193189 and palovarotene." (PMID 37373155, 2023). "Treatment with Smad1/5/8 inhibitors, LDN193189, and palovarotene reduced cancer malignancy and chemoresistance in PCTK1-KD and PCTK1-KO cells." (PMID 37373155, 2023). "(E) Integrative analysis of RNAscope and mfIHC data indicates that cancer tissues with high levels of VPS9D1-AS1 had higher levels of TGF-β, TGFBR1, and SMAD1/5/9 than these with low levels of VPS9D1-AS1." (PMID 36458816, 2022). "SMAD1 protein was involved in the regulation of the TGF-β signaling pathway, which was reported to be abnormally expressed and involved in regulating cancer metastasis of multiple cancers, including NSCLC." (PMID 33996578, 2021). "Previous studies from others and us demonstrated that bone morphogenetic protein-independent Smad1/5 signaling activation of shear force stimulation could result in the cell cycle arrest, differentiation inhibition and cell death of different types of cancer cells." (PMID 32630668, 2020). "pERK will phosphorylate SMAD3 through SMAD1 that eventually translocate SMAD4 to the nucleus and activate collagen production genes in cancer cells." (PMID 33294017, 2020). "For instance, it was reported that the miR-26b inhibits the metastatic spreading of this cancer through both its CTGF and Smad1 direct targeting." (PMID 30515265, 2018). "The next step is to see how the signaling via SMAD1 and SMAD5 contributes to different aspects of cancer development." (PMID 29376829, 2018). "Unexpectedly, tumors from scirrhous carcinoma clones, i.e. clones showing low levels of BMP-6 mRNA expression in vitro and a low degree of Smad-1/5 pathway activation, were strongly positive for BMP-6 protein." (PMID 19771160, 2009). "Smad-1/5-dependent signaling includes the transcriptional activation of inhibitor of differentiation proteins (ID1–3), which regulate cancer cell metastasis and stemness of cancer stem cells." (PMID 39315260, 2024). "Moreover, ZEB2 correlates with SMAD1 in 28 cancer types, SMAD2 in 27 cancer types, SMAD3 in 22 cancer types, SMAD5 in 28 cancer types, CTBP1 in 14 cancer types, and CTBP2 in 22 cancer types." (PMID 35723302, 2022). "KEGG analysis showed that ACVR1, SMAD1, ZFYVE9, BMPR1B, and TGFB3 were related to regulating proteoglycan in cancer, focal adhesion, tight junction, PI3K-Akt signaling pathway, cell adhesion molecules (CAMs), Rap1 signaling pathway, osteoclast differentiation, and Hippo signaling pathway." (PMID 34725559, 2021).
cancer (continued). "Recent studies have shown that bone morphogenetic protein receptor 2 (BMPR2) regulates cell survival signaling events in cancer cells independent of the BMP type 1 receptor (BMPR1) or the Smad-1/5 transcription factor." (PMID 34563224, 2021). "TGF-β, one role in the pathogenesis of carcinoma, could regulate VEGF release in an ALK-5-dependent manner by SMAD2/3 versus SMAD1/5/8 signalling." (PMID 32308722, 2020). "Same prognostic trends and positive correlation between the expression levels of FSTL1, BMP4, p-Smad1/5/8, and Smad4 indicates FSTL1 may regulate cancer progression through BMP4-p-Smad1/5/8-Smad4 signaling." (PMID 28852126, 2017). "Interestingly, several of these TFs (e.g., NKX3-1, SMAD1/3, SRF, ETV4 and ELK1) are known to play important roles in PCa, as well as in other types of cancer." (PMID 24968068, 2014). "Interestingly, positively correlated loci represented cancer driver genes (MYC, PRKCD, RB1, CDK6), molecules involved in immune response (MALT1, PIK3CG), as well as cellular and hormonal signaling (HGF, PTPN13, IGF1, SMAD1, ESR1, CTGF)." (PMID 34368147, 2021). "The activation of Smad-1/5/8 observed in RGMB knockdown cells could have resulted in transcriptional regulation of BMP-responsive genes, and enhanced invasion and migration of cancer cells." (PMID 26910889, 2016). "Interestingly, phosphorylation of Smad1/5 at Ser463/465, which has been implicated in epithelial-mesenchymal transition, was obviously induced in cancer cells by CAFs-derived CM, suggesting CAFs might be able to exert pro-metastatic role via LRG1-mediated activation of Smad1/5 signaling." (PMID 34930899, 2021). "Thus, preferential activation of the Smad1 linker domain may provide a novel therapeutic approach for treating DN without exerting undesirable adverse effects such as cancer, which is induced by the direct inhibition of Smad343,44." (PMID 30002389, 2018). "This SMAD1/5 arm of TGF-β signaling has also been shown to occur in a wide range of other cell types, including epithelial cells, fibroblasts and cancer cell lines, which do not express ACVRL1." (PMID 29376829, 2018).
infection (11 papers, 2012 to 2024). The state of being infected such as from the introduction of a foreign agent such as serum, vaccine, antigenic substance or organism. "Infection with all ACVR1 mutations led to increased phosphorylated SMAD1/5/8 expression as compared to ACVR1 WT, with ACVR1 G328E increasing pSMAD1/5/8 modestly but significantly relative to ACVR1 WT." (PMID 30833574, 2019). "Infection with L. monocytogenes causes H3K18 deacetylation of many genomic proteins in colon cells, including SMAD1, IRF2, SMARCA2, and CXCL12." (PMID 35572672, 2022). "ZIKV suppressed BMP6 expression as well as the downstream signaling as evidenced by decreased phosphorylation of SMAD1/5 at the later stages of infection." (PMID 36713156, 2022). "Our study revealed that the infection with the active form of AMPK progressively reduced phosphorylation of Smad1/5 induced by BMP6, concomitant with elevation of Smad6." (PMID 33169942, 2020). "We also found that the expression of phosphorylation of SMAD1/5/8 and SMAD4 were increased by 2.4 and 2.1 fold respectively at 8 hr of infection than at 4 hr and untreated which is generally accepted as readout of an active BMP pathway by Western blot." (PMID 25365201, 2014). "Furthermore, although metformin effectively inhibited BMP9-induced responses in HFL-1 cells infected with GFP-AD, AMPK-DN infection offset the inhibitory impact of metformin on the up-regulation of ALK1 and p-Smad1/5 by BMP9." (PMID 36091775, 2022). "Gene expression analysis showed that Smad2 is significantly down-regulated while Smad1 and the activin receptor gene Acvr1b are up-regulated in the resistant BALB/c mouse during infection, but not in the susceptible CBA/Ca." (PMID 24594938, 2014). "At early stages of infection (3 hpi), HFF-1 infected with either HCMV US18stop, HCMV US20stop, or HCMV US18/20stop displayed a strong phosphorylation of SMAD1/5/9 already in the absence of BMP9 stimulation, potentially due to endogenously secreted BMP9." (PMID 38308064, 2024).
adenocarcinoma (3 papers, 2016 to 2023). A common cancer characterized by the presence of malignant glandular cells. "The results indicated that there were significant positive correlations among FSTL1, BMP4, Smad4, and p-Smad1/5/8 IHC expression in adenocarcinoma." (PMID 28852126, 2017).
skeletal dysplasia (3 papers, 2021 to 2022). Any Mendelian diseases that affects growth and development of the skeleton. "Importantly, a subset of TAPT1 mutations identified in humans with lethal skeletal dysplasia exhibited gain-of-function activity on SMAD1 protein levels." (PMID 36370851, 2022). "SMAD1 was one of the essential molecules in the BMP/SMAD pathway critical for bone metabolism, and NKX3‐2 was reported to relate with skeletal dysplasia." (PMID 35297204, 2022).
bacterial infection (1 paper, 2021). "As the two inhibitors with their proposed effects on SMAD1/5/9 signaling showed neither an inhibitor effect nor altered STAT3 phosphorylation, other hepcidin inducing pathways may play a dominant role during bacterial infection." (PMID 34368018, 2021).
hematological malignancies (1 paper, 2021). "We found a moderate but highly significant negative correlation between high SMAD1 expression and KEGG Apoptosis pathway inhibition across the ~ 1000 CCLE cell lines (R = -0.1486, p < 0.0001); an enrichment of apoptosis inhibition (high Z score) was also observed in other hematological malignancies." (PMID 34134766, 2021).
neurodegenerative disease (1 paper, 2024). A disorder of the central nervous system characterized by gradual and progressive loss of neural tissue and neurologic function. "Therefore, as the pathology progresses in both human samples and mouse models, the expression of SMAD1, -5, -8 mRNA, and protein increases in neurodegenerative diseases, suggesting that these changes can be used as disease progression markers." (PMID 39057101, 2024).
SMAD1 also shares sentences with these, for which no sentence is quoted: multiple myeloma (5 papers); pulmonary hypertension (3); glaucoma (2); Hepatic steatosis (2); kidney diseases (2); myopia (2); neurological diseases (2); Parkinson disease (2); type 2 diabetes (2); achondroplasia (1); acute myocardial infarction (1); Anxiety (1); aortic aneurysm (1); benign glioma (1); bladder cancer (1); bladder urothelial carcinoma (1); brain infarction (1); brain injury (1); brain tumour (1); cartilage tumours (1); chronic hepatitis C (1); chronic lymphocytic leukemia (1); congenital heart disease (1); COVID-19 (1); diabetic neuropathy (1); diabetic retinopathy (1); female infertility (1); fibrosarcoma (1); fibrosis (1); follicular lymphoma (1).
A further 40 diseases each share a sentence with SMAD1 in 1 paper.